EGFR (epidermal growth factor receptor)
Diseases named in the same sentence as EGFR in open-access papers (continued):
Sharing a sentence is not in itself a finding about the gene and the disease.
lung cancer (continued). "Because 4G EGFR-TKIs are active against two major secondary mutations, T790M and C797S, it is reasonable that each lung cancer cell line acquired a “preferred” off-target resistance mechanism." (PMID 39061985, 2024). "EGFR-variant non–small cell lung cancer (NSCLC) is associated with a high rate of central nervous system (CNS) metastases, even with treatment with first-generation or second-generation epidermal growth factor receptor (EGFR) tyrosine kinase inhibitors (TKIs)." (PMID 39145962, 2024). "EGFR-TKI, the current first-line therapy for NSCLC harboring EGFR mutations, is encountering the clinical challenge of primary resistance in patients with wt-EGFR lung cancer." (PMID 38764025, 2024). "For example, several studies have explored the performance of radiomics for epidermal growth factor receptor (EGFR) mutation status prediction in lung cancer." (PMID 39075486, 2024). "DL outperforms radiomics in predicting EGFR mutations in lung cancer and has advantages in gene prediction for other cancers." (PMID 39619439, 2024). "In those with lung cancer BrMs, EGFR mutations were most frequent in the iCNS compared to cCNS and eCNS groups (67% vs 40% vs 37%, P = .08)." (PMID 38680992, 2024). "Previous studies have highlighted striking geographic and ethnic variations in EGFR mutation–positive lung cancer." (PMID 38954434, 2024). "The expression of EGFR is also linked with major markers, contributing to lung cancer development and progression." (PMID 39453005, 2024). "Osimertinib plus chemotherapy is not cost‐effective compared to osimertinib alone for treatment‐naïve patients with EGFR‐mutated advanced non‐small cell lung cancer in the United States." (PMID 39206619, 2024). "For instance, the T790M acquired mutations in Epidermal Growth Factor Receptor (EGFR) were associated with resistance to the tyrosine kinase inhibitors inhibitor (afatinib, erlotinib and gefitinib) in lung cancer." (PMID 38227591, 2024). "Epidermal growth factor receptor tyrosine kinase inhibitors (EGFR‐TKIs) are the standard treatment choice for advanced non‐small cell lung cancer (NSCLC) patients with EGFR mutations." (PMID 39631794, 2024). "Integrating SUVmax, EGFR mutation status, and PD-L1 expression provides a comprehensive framework for distinguishing pseudo-progression from hyper-progression in lung cancer." (PMID 39902124, 2024). "Erlotinib, an EGFR inhibitor, has previously been demonstrated to reduce cell viability by inducing autophagy in lung cancer cell lines with varying EGFR mutations." (PMID 39057088, 2024). "The epidermal growth factor receptor tyrosine kinase inhibitors (EGFR-TKI) gefitinib and erlotinib, used in adjuvant chemotherapy, showed significant antitumor activity in lung cancer with EGFR gene mutation." (PMID 39165682, 2024). "In EGFR-mutated lung cancer, the duration of response to tyrosine kinase inhibitors (TKIs) is limited by the development of acquired drug resistance." (PMID 39122703, 2024). "Together, our findings support the use of high-throughput genetic screening to understand EGFR variant functionality in models of lung cancer." (PMID 38548752, 2024). "One is epiregulin (EREG), a ligand for the EGFR receptor; EGFR is a known pathway important to lung cancer development and involved in the proliferative hallmark of cancer." (PMID 39771097, 2024). "For example, drugs such as imatinib for chronic myeloid leukemia and erlotinib for EGFR-mutated lung cancer have transformed treatment paradigms by specifically targeting cancer-driving mutations." (PMID 39767566, 2024). "Roughly half of patients with lung cancer exhibit EGFR mutations, with a notable increase in EGFR protein expression in LSCC compared with LUAD." (PMID 39544292, 2024). "Our review aims to summarize the adverse renal effects caused by targeted therapy during lung cancer treatment, mainly focusing on EGFR and ALK tyrosine kinase inhibitors." (PMID 39026680, 2024).
lung cancer (continued). "In conclusion, we have reported the case of a rare EGFR T790M germline mutated patient with confirmed family history developing lung cancer who achieved clinical benefit from Osimertinib treatment." (PMID 39160638, 2024). "A total of 771 EGFR tests were conducted on stage IV lung cancer patients, diagnosing 141 patients with EGFR mutation during the period 2017–2021, with a prevalence of 18%." (PMID 39421175, 2024). "Another study has found similar results in evaluating the risk of lung cancer where the homozygous variant AA of SNP rs6721961 C>A was significantly associated with EGFR mutations." (PMID 39026573, 2024). "Research has found an interesting phenomenon: in lung cancer patients under 50 years old, there is a higher proportion of lung cancer with targetable genomic changes, such as EGFR mutations, ALK or ROS1 fusions, or ERBB2 insertions." (PMID 38756780, 2024). "Identifying new predictive biomarkers is vital for the development of targeted therapies for lung cancer, especially therapies for overcoming resistance to drugs such as osimertinib in EGFR-mutated NSCLC." (PMID 38689087, 2024). "Similar associations were recapitulated in various EGFR-mutant lung cancer cell lines including HCC827, NCI-H1975, and NCI-H820." (PMID 39604408, 2024). "Describe the prevalence and identify factors associated with survival in stage IV lung cancer patients harboring EGFR mutations in a real-world setting." (PMID 39421175, 2024). "KRAS and EGFR driver mutations in lung cancer differentially affect both drug transporter expression and cisplatin-induced WNT signaling, impacting responsiveness of the tumor to treatments." (PMID 38474205, 2024). "The proportion of patients with lung carcinoma that harbors EGFR mutation varies globally with 6% reported in African American patients, 15% in Europeans, 23% in Indians, 35% in Hispanics and 47% in Asians." (PMID 39021550, 2024). "In non–small cell lung cancer (NSCLC), the major form of lung cancer, the activating mutation of EGFR is an important oncogenic driver." (PMID 39041204, 2024). "Common genetic mutations in lung carcinoma include EGFR, KRAS, EML4-ALK, Ros1, and c-MET, among others." (PMID 38571504, 2024). "In contrast, the highest frequency for the interface mutations of EGFR is 0.007%, from the samples of large intestine and lung carcinoma." (PMID 38216592, 2024). "Several prior studies have shown that most EGFR-mutated lung cancer cells die within a few days after EGFR-TKI treatment; however, DTCs remain detectable." (PMID 36831438, 2023). "Currently, imaging omics studies for predicting lung cancer gene mutations primarily focus on the EGFR gene mutations, which are the most prevalent mutations in clinical practice." (PMID 38027000, 2023). "Currently, detecting EGFR p.(Tyr790Met) mutation in plasma samples from lung cancer patients has been used for predicting response and monitoring tyrosine kinase inhibitors (TKi)-treated patients with lung cancer." (PMID 36768828, 2023). "Another commonly mutated genetic driver in lung cancer is the epidermal growth factor receptor (EGFR), which is mutated in up to 25% of lung cancer patients." (PMID 36678835, 2023). "Molecularly targeted drugs such as EGFR and TKIs are effective in patients with EGFR or ALK mutations in lung cancer." (PMID 37326149, 2023). "Three genes (BDH1, DDX49 and EGFR) were associated with lymph node metastases of lung cancer, and BDH1 gene had a highest predictive capacity for lymph node metastases and distant metastases through multivariate logistic regression." (PMID 36919822, 2023). "The clinical development of EGFR-TKIs offered a more efficacious and tolerable alternative to standard cytotoxic chemotherapy for patients with EGFR-mutated lung cancer, and this has profoundly altered the NSCLC treatment landscape in the past decade." (PMID 36895484, 2023).
lung cancer (continued). "Risk factors for increasing the likelihood of lung nodule carcinogenesis include the following: current or previous smoking, older, personal cancer history, family history of lung cancer, emphysema, exposure to asbestos or radon and EGFR mutation." (PMID 37371643, 2023). "In KRAS-mutated lung cancer cells treated with EGFR inhibitors, NFkB is involved in the upregulation of type I interferons (IFNs)." (PMID 37483492, 2023). "In accordance with this results, analyses of tumour samples from lung cancer patients with EGFR mutations revealed a significant inverse correlation between MIG-6 expression their survival rates after the treatment with EGFR-TKI." (PMID 36701089, 2023). "Except for smoking history, better performance status at the last follow up and targeted therapy for EGFR or ALK mutation significantly improved survival rates for metastasis of lung cancer." (PMID 37510797, 2023). "A great number of lung cancer biomarkers have been identified such as EGFR mutations, ALK and ROS-1 rearrangements, and HER-2 overexpression." (PMID 38188023, 2023). "A combination of a weak driver and a strong driver mutation T790/L858 double mutation in EGFR is present in one cell line of lung cancer." (PMID 36808143, 2023). "Biological and genetic factors associated with lung cancer include chronic lung diseases, infections, positive family history, and various genetic alterations (such as mutations in the EGFR, KRAS, BRAF, ERRB2 genes, among others)." (PMID 37373500, 2023). "If the tumor has L858R EGFR mutations or exon 19 deletions, lung cancer patients can be treated with TKIs, erlotinib, or gefitinib." (PMID 37508387, 2023). "Another study showed that the presence of EGFR mutations was a risk factor for distant metastasis in early-stage lung cancer." (PMID 38067382, 2023). "According to The Cancer Genome Atlas (TCGA), the most common mutations occurring in lung cancer affect KRAS (Kirsten rat sarcoma virus) or EGFR (epidermal growth factor receptor)." (PMID 36678835, 2023). "This study aimed to identify prognostic factors and develop a prognostic system exclusively for epidermal growth factor receptor (EGFR)-mutated lung cancer BM." (PMID 37020869, 2023). "Apart from L858R mutation, we found another exon 21 mutation L861X, including L861Q and L861R, in 2.3% of all EGFR mutations and 5.7% of rare EGFR mutations in the GENIE lung cancer dataset." (PMID 36830579, 2023). "For example, spheroid models have been used to test the response of lung cancer cells with specific mutations (e.g., EGFR mutations) to targeted drugs like EGFR inhibitors (e.g., erlotinib)." (PMID 37894363, 2023). "Tumor genotype plays an important role in personalized treatment for lung cancer patients, where mutations in common proto-oncogenes and oncogenes such as EGFR, ALK, ROS1, and RET have been associated with radiomic signatures see 11 for review." (PMID 37990050, 2023). "Studies have reported that most BM originating from lung cancer is located in the supratentorial area of the brain and its distribution depends on the mutational status of EGFR." (PMID 36765679, 2023). "A mate-analysis showed that for patients with tissue EGFR-mutated lung cancer, the therapeutic benefit of EGFR-TKIs was similar in the ctDNA+ and ctDNA− subgroups." (PMID 36835972, 2023). "Lung cancer cells have a high incidence of EGFR amplification, which can affect the abundance of EGFR mutations, as determined by the ARMS assay." (PMID 37754531, 2023). "This study aimed to determine the effectiveness of liquid biopsy in detecting EGFR, an executive mutation that causes lung cancer." (PMID 38304031, 2023). "Patritumab deruxtecan demonstrated both efficacy and safety in a phase I trial involving patients with EGFR-mutated lung cancer that progressed after TKI treatment." (PMID 37894376, 2023).
lung cancer (continued). "The objective of this review is to evaluate existing data on the outcomes, epidemiology, and clinical characteristics of lung cancer patients with rare EGFR mutations, with a focus on intracranial activity and response to immunotherapy." (PMID 37240224, 2023). "EGFR is the protein encoded by the proto-oncogene c-erbB1, which is a member of the EGFR receptor family and is highly expressed in lung cancer." (PMID 36910653, 2023). "KRAS mutated lung cancer have been linked with incremented glycolytic flux and this is also the case also for EGFR mutant tumors, in which the activation of PIP3K/AKT/mTORC1 supports glycolysis and consequently fosters cell proliferation." (PMID 37180110, 2023). "EGFR tyrosine kinase inhibitors (EGFR-TKIs) are effective in treating EGFR-mutated lung cancer, whereas they have thus far shown little activity in colorectal cancer." (PMID 37974093, 2023). "The treatment of lung cancer has also evolved with the introduction of several lines of tyrosine kinase inhibitors (TKIs) in patients with EGFR, ALK, ROS1, and NTRK mutations." (PMID 37371816, 2023). "The introduction of tyrosine kinase inhibitors has greatly improved the survival of lung cancer patients with EGFR mutations." (PMID 37201304, 2023). "Osimertinib monotherapy is one of the standard treatments for patients with EGFR-mutated lung cancer." (PMID 37760942, 2023). "Epidermal growth factor receptor (EGFR) mutations are the most common driver mutation in lung cancer." (PMID 38140788, 2023). "Genetic alterations, such as EGFR-activating mutations, are identified as the essential promoter of lung cancer development." (PMID 37181807, 2023). "The International Association for the Study of Lung Cancer (IASLC) recommends to test EGFR mutations and ALK and ROS1 fusions." (PMID 36899890, 2023). "This work also showed that EGFR lung cancer mutations overcome the autoinhibitory block of the head‐to‐head interface, thereby becoming constitutively activated losing the regulation provided by the ligand." (PMID 36282005, 2023). "This included a relatively high prevalence of epidermal growth factor receptor (EGFR) mutations in lung cancer." (PMID 37702806, 2023). "KRAS mutations in NSCLC are more frequent (about 30% of cases) than EGFR mutations (15%), which is in agreement with smoking frequency in lung cancer patients." (PMID 36817482, 2023). "In this observational study, we evaluated the association between osimertinib treatment and plasma concentration in previously treated EGFR mutation-positive lung cancer." (PMID 37760942, 2023). "Unlike other cancers with specific mutations such as BRCA1/2 in breast cancer and EGFR in lung cancer, ESCC lacks tumor-specific mutations." (PMID 37553345, 2023). "ErbB family members play an important role in the occurrence and maintenance of various solid tumors, especially HER2-amplified breast cancer and epidermal growth factor receptor (EGFR) mutated lung cancer." (PMID 38017514, 2023). "The discovery of potent EGFR-tyrosine kinase inhibitors (EGFR-TKIs) has revolutionized the treatment of EGFR-mutated lung cancer." (PMID 36902280, 2023). "Lung cancer EGFR mutation status was obtained from Samsung Medical Center lung cancer diagnoses for the years 2017 to 2018 for 16 geographical regions across Korea (n = 2,563)." (PMID 37020004, 2023). "TAS-116 was thus suggested as a novel drug to overcome tyrosine kinase inhibitor resistance in both GIST and EGFR-mutated lung cancer." (PMID 38275722, 2023).
lung cancer (continued). "Both drugs have been approved by the FDA for the treatment of EGFR exon 20 insertion-mutated lung cancers." (PMID 37622996, 2023). "successfully deleted a panel of oncogenes in lung cancers, including those encoding for epidermal growth factor receptor (EGFR), CD38, focal adhesion kinase (FAK), NESTIN, remodeling and spacing factor 1 (RSF1), and catenin delta 2 (CTNND2)." (PMID 37356052, 2023). "Our studies reveal that 8PN has the potential for further development as an adjuvant for the treatment of lung cancer patients with EGFR mutations." (PMID 37013960, 2023). "Collectively, these findings point towards a potential role of AhR in air pollution-mediated lung ADCs with EGFR driven mutations and lung cancer." (PMID 37696458, 2023). "A training set of pretreatment H&E-stained pathology images was derived from 168 patients with sensitizing EGFR mutations enrolled in the multi-institutional Lung Cancer Mutation Consortium 1 (LCMC1)." (PMID 36647832, 2023). "EGFR targeted therapy is mainly used for lung cancer especially non-small cell lung cancer (NSCLC) that has EGFR mutations or amplification." (PMID 37483616, 2023). "One proven cause of unfavorable outcomes in MET altered lung cancer is acquired resistance to EGFR TKIs, underlining the need for more efficient targeted therapies." (PMID 37568643, 2023). "Treatment with tyrosine kinase inhibitors (TKIs) has brought significant benefits to lung cancer patients with EGFR mutations." (PMID 36778111, 2023). "The plasma sample has emerged as a promising surrogate sample for EGFR mutation detection in advanced non‐small cell lung cancer (NSCLC)." (PMID 36621813, 2023). "To explore the effects of AICAR treatment on lung cancer cell lines, we performed a cell viability assay using a panel of lung cancer cell lines based on the status of EGFR mutations." (PMID 36810913, 2023). "Targeting EGFR alterations, particularly the L858R (Exon 21) mutation and Exon 19 deletion (del19), has significantly improved the survival of lung cancer patients." (PMID 37958668, 2023). "Institutional lung cancer incidence and EGFR mutation rates for each of 12 different counties in Taiwan were obtained from the Chang Gung Research Database for the years 2011–2017 (n = 4,599)." (PMID 37020004, 2023). "In EGFR-mutated lung cancer cell models, EGFR mutation leads to downregulation of miR21 expression, which stabilizes TNF mRNA and activates the TNF, thereby activating NFkB signaling pathways." (PMID 37483492, 2023). "The existing results suggested that no evident synergistic effects of the combination of ICIs and anti-EGFR inhibitors in EGFR-mutated lung cancer were observed, and this combined strategy only induced a lower response rate and more toxicities." (PMID 37345194, 2023). "These dysregulated miRNAs also interact with various signaling pathways that are frequently mutated in lung cancer, such as the EGFR and KRAS pathways, further highlighting their roles in the disease." (PMID 37631277, 2023). "Gene amplification and mutations of EGFR have been implicated in the pathogenesis and progression of many malignancies, including lung cancer." (PMID 37240137, 2023). "In total, 173 patients with EGFR-mutated lung cancer from two hospitals who developed BM and received tyrosine kinase inhibitor (TKI) and brain radiation therapy (RT) were included." (PMID 37020869, 2023). "In lung cancer, certain genetic mutations, including those in the epidermal growth factor receptor (EGFR), lead to overactivation of tyrosine kinases, promoting tumor progression and malignancy." (PMID 37509204, 2023). "In summary, our results showed that expression of the lncRNA BC was closely associated with lung cancer cell proliferation and metastasis, poor patient survival and resistance to EGFR‐TKIs." (PMID 36650118, 2023).